ZNF850 (zinc finger protein 850)
Description:
May be involved in transcriptional regulation.
Synonyms: ZNF850P
Tractability: PROTAC: ubiquitination databases record sites on it.
Gene: Protein-coding gene on chromosome 19 (36,714,383 to 36,772,825, reverse strand). Ensembl gene ENSG00000267041.
Subcellular location: Nucleus
Subcellular location (Human Protein Atlas): Nucleoplasm
Gene Ontology:
Molecular function: transcription cis-regulatory region binding
Biological process: regulation of transcription by RNA polymerase II; in utero embryonic development; regulation of DNA-templated transcription
Cellular component: nucleus
Genetic constraint (gnomAD): Loss-of-function variants: 3 observed, 5.7 expected, observed/expected ratio (o/e) 0.53, 90% interval 0.24 to 1.34. That is too few expected variants to judge how well the gene tolerates losing a copy. Missense variants: 988 observed, 1,097.4 expected, observed/expected ratio (o/e) 0.9, 90% interval 0.85 to 0.95. Synonymous variants: 371 observed, 361.15 expected, observed/expected ratio (o/e) 1.03, 90% interval 0.94 to 1.12.
Homologues: Orthologues: chimpanzee ZNF850 (92% identical), mouse Zfp619 (37% identical), rat Zfp619 (36% identical), macaque ZNF594 (34% identical), rat Zfp788 (29% identical). Paralogues in human: PRDM5 (16% identical), ZNF668 (16% identical), ZNF358 (13% identical), ZNF579 (10% identical).
Diseases named in the same sentence as ZNF850 in open-access papers:
ZNF850 is named in the same sentence as 1 disease in open-access papers, as found by Europe PMC text mining. Sharing a sentence is not in itself a finding about the gene and the disease.
ZNF850 shares sentences with these, for which no sentence is quoted: cancer (1 paper).